SLC9A7 (solute carrier family 9 member A7)
Description:
Golgi Na(+), K(+)/(H+) antiporter. Mediates the electoneutral influx of Na(+) or K(+) in exchange for H(+). May contribute to the regulation of Golgi apparatus volume and pH.
Synonyms: NHE-7; NHE7; MRX108
Tractability: Antibody: UniProt places it where antibodies can reach, with high confidence; its Gene Ontology location is reachable by antibodies, with high confidence; UniProt predicts a signal peptide or a membrane-spanning region. PROTAC: it is named in the literature on targeted protein degradation; ubiquitination databases record sites on it; its protein half-life has been measured.
Gene: Protein-coding gene on chromosome X (46,599,251 to 46,759,193, reverse strand). Ensembl gene ENSG00000065923.
Subcellular location: Golgi apparatus, trans-Golgi network membrane; Recycling endosome membrane; Cell membrane
Subcellular location (Human Protein Atlas): Vesicles
Pathways (Reactome):
Transport of small molecules: Sodium/Proton exchangers
Gene Ontology:
Molecular function: potassium:proton antiporter activity; protein binding; sodium:proton antiporter activity; antiporter activity
Biological process: Golgi lumen acidification; regulation of intracellular pH; sodium ion import across plasma membrane; sodium ion transmembrane transport; monoatomic cation transport; potassium ion transmembrane transport; proton transmembrane transport; regulation of pH; sodium ion transport; transmembrane transport
Cellular component: membrane; plasma membrane; recycling endosome membrane; trans-Golgi network; Golgi membrane; recycling endosome; Golgi apparatus
Homologues: Orthologues: macaque SLC9A7 (99% identical), chimpanzee SLC9A7 (97% identical), rabbit SLC9A7 (97% identical), dog SLC9A7 (97% identical), guinea pig SLC9A7 (96% identical), pig SLC9A7 (96% identical), rat Slc9a7 (95% identical), mouse Slc9a7 (95% identical), tropical clawed frog slc9a7 (80% identical), zebrafish slc9a7 (76% identical), Caenorhabditis elegans nhx-2 (19% identical), Caenorhabditis elegans nhx-6 (19% identical). Paralogues in human: SLC9A6 (66% identical), SLC9A9 (54% identical), SLC9A8 (26% identical), SLC9A2 (23% identical), SLC9A5 (23% identical), SLC9A3 (23% identical), SLC9A4 (22% identical), SLC9A1 (22% identical), SLC9C1 (15% identical), SLC9C2 (13% identical).
Diseases named in the same sentence as SLC9A7 in open-access papers:
SLC9A7 is named in the same sentence as 12 diseases in open-access papers, as found by Europe PMC text mining. Sharing a sentence is not in itself a finding about the gene and the disease. The quoted sentences say what the papers report.
Intellectual disability (2 papers, 2020 to 2024). "It is also relevant that genetic variation on SLC9A7 has been shown to be associated with intellectual disability, such that variants with strong regulatory effects may in fact be selected against and thus not observed in an AD XWAS." (PMID 39250132, 2024).
autism (1 paper, 2021). Persistent deficits in social interaction and communication and interaction as well as a markedly restricted repertoire of activity and interest as well as repetitive patterns of behavior. "On the contrary to our expectations, dog cfa6.7 that also maps in GALNT17, aligns with three different human genes (NRXN3, SLC9A7 and 15 kb upstream SPRY3) that are already involved in autism, two of which are X-linked." (PMID 34680999, 2021).
pancreatic ductal adenocarcinoma (1 paper, 2023). An infiltrating adenocarcinoma that arises from the epithelial cells of the pancreas. "For example, inhibiting solute carrier family 9 member A7 (SLC9A7, also known as NHE7) induces Golgi alkalization, causing cytosolic acidification and abolishing pancreatic ductal adenocarcinoma tumor growth." (PMID 37601110, 2023).
tumor (6 papers, 2023 to 2026). "Additionally, genetic suppression of the membrane pH regulator solute carrier family 9 member A7 (SLC9A7/NHE7) also leads to alkalinization and tumor suppression in preclinical PDAC models." (PMID 38994937, 2024).
cancer (4 papers, 2021 to 2022). A tumor composed of atypical neoplastic, often pleomorphic cells that invade other tissues. "The bar plot generated by GEPIA2 clearly showed that the expressions of SLC9A2, SLC9A3, and SLC9A9 in COAD tissues were obviously lower than those in normal tissues, but SLC9A5 and SLC9A7 in cancer were distinctly higher than those in normal tissues." (PMID 34759967, 2021).
SLC9A7 also shares sentences with these, for which no sentence is quoted: breast carcinoma (1 paper); coronary atherosclerosis (1); endometrial cancer (1); hepatocellular carcinoma (1); ischemic heart disease (1); pancreatic cancer (1); X-linked intellectual disability (1).